ENSG00000287449 (novel transcript)
Gene: Long non-coding RNA gene on chromosome 4 (140,577,845 to 140,579,657, forward strand). Ensembl gene ENSG00000287449.
Gene Ontology:
Biological process: SRP-dependent cotranslational protein targeting to membrane, signal sequence recognition
Cellular component: signal recognition particle, endoplasmic reticulum targeting